CD33 (CD33 molecule)
Diseases named in the same sentence as CD33 in open-access papers (continued):
Sharing a sentence is not in itself a finding about the gene and the disease.
cancer (continued). "MDSCs are a heterogeneous population of cells which expand during cancer, inflammation and infection, with a remarkable ability to suppress T-cell responses, and were defined as CD11b+ CD14- CD33+ in most tumors." (PMID 35069553, 2021). "However, in contrast with several previous studies in cancer, but consistently with a recent study by de Kleijn and colleagues, we demonstrate that the LDNs subset in the circulation of TB patients express significantly elevated levels of CD66b, CD33, CD16, and CD15, as compared to the NDNs subset." (PMID 31849955, 2019). "To date, MDSCs have been defined mainly as HLA-DR−, CD11b+, CD33+, and CD15+ lineages in human cancers." (PMID 25238263, 2014). "Taken collectively with our survey of CD33+ MDSC induction, these data suggest that the induction of MDSC is a universal feature of human cancers with some variation in the phenotype of induced MDSC subsets observed." (PMID 21658270, 2011). "In cancer patients, these cells express the common myeloid marker CD33 but not mature myeloid and lymphoid cell markers in cancer patients." (PMID 36793738, 2023). "This approach would allow us to avoid the undesirable effects on the physiological function of P-gp, providing natural inhibitors in nanosystems targeting cancer cells and resistant leukemic stem cells that overexpress efflux pumps, i.e., using this possibility in AML to target CD33 positive cells." (PMID 36835550, 2023). "In another recent study sunitinib reduced non-classical CD33+ CD14+ CD16+ MDSCs in the blood of cancer patients by apoptosis and the rest of CD33+ CD14+ CD16+ MDSCs showed less pSTAT3, ArgI and less suppressive activity on T-cell proliferation." (PMID 27886105, 2016). "We further confirmed a strong positive correlation between NLRC4 expression with myeloid lineage markers from the TCGA data set, including specific macrophage marker CD163 and common myeloid markers CD68 and CD33, suggestive of a myeloid origin of NLRC4 in human cancer." (PMID 27708283, 2016). "Lastly these studies suggest that CD33+HLA-DRlowHIF1α+ and CD11b+HLA-DRlowC/EBPβ+ are highly specific phenotypes that may be used to isolate and study MDSC in cancer patients." (PMID 21658270, 2011). "We highlight differential expression of STAT3/HIF1 α and C/EBPβ in the CD33+ and CD11b+ subsets, respectively, that may aid other investigators in therapeutic targeting, subset expansion, or MDSC monitoring in cancer patients." (PMID 21658270, 2011). "Notably, for both CD33−- and CD37CAR T cell-treated mice, the recurrence of cancer cells in the PDX model was not due to antigen loss." (PMID 38754420, 2024). "However, we were not able to fully determine the prognostic value of CD33 in cancer subtypes herein, given the limited nature of our clinical data." (PMID 35493454, 2022). "Interestingly, a large portion of the isolated CD33+CD11b+HLA-DRlow/− did not meet the classic criteria of G- or M-MDSCs as defined in the cancer literature." (PMID 31722736, 2019). "Therefore, we tested whether soluble MICA (shed from the cell surface by proteolytic cleavage, found at levels up to 1–50 ng/mL in the sera of patients with cancer including AML, and representing a dominant soluble NKG2D ligand in AML patients) and/or CD33 could interfere with CC-96191 cytotoxicity." (PMID 38473239, 2024). "Interestingly, addition of CD33+ MDSCs in both Jurkat and Raji cell culture accelerated the generation of drug-resistance, as evidenced by significant upregulation of P-gp, MRP expression just only after 3 cycles of Dox-treatment and designated as early passage (EP) cancer cells." (PMID 38304256, 2023). "In addition, administration of anti-CD33/CD3 antibody (AMG 330) triggered T cell-mediated lysis of AML blasts that was further enhanced by T cell elimination of IDO+CD33+ MDSCs (IDO, an enzyme released by cancer cells to deplete tryptophan leading to suppressed T cell activities)." (PMID 33718188, 2021).
cancer (continued). "MDSCs in cancer patients were characterized by the expression of CD14, CD11b, CD33, and Arg1, along with low or absent expression of HLA-DR." (PMID 37865804, 2023). "Recent data interrogating the TCGA show upregulation of TGF-β1 in a number of cancers including CRC and this correlates with the markers expressed on M-MDSCs, CD14 and CD33, but not with the G-MDSC marker CD66b (PMN-MDSCs are CD33dim rather than the high expression seen on M-MDSCs)." (PMID 34727230, 2022). "Although not previously shown to be directly related with cancers, several surface markers, such as CD19 and CD34, showed significant positive correlation (Pearson R > 0.5) with RUNX1T1 in RNA levels, whereas CD33 showed negative correlation (Pearson R = −0.36)." (PMID 30959925, 2019). "Similarly, elimination of MCSPpos cancer cells by scFvFITC:sTRAIL was only observed when pretargeted with anti-MCSP-FITC, whereas pretargeting with an irrelevant anti-CD33-FITC antibody failed to do so." (PMID 29038485, 2017).
infection (29 papers, 2008 to 2025). The state of being infected such as from the introduction of a foreign agent such as serum, vaccine, antigenic substance or organism. "The authors suggested that the immune dysregulation caused by the infection leads to the autoimmune manifestation, mediated by the action of CD33 + CD11b + HLA-DR+ cells and that the frequency of these cells decreased with the use of HAART." (PMID 37298611, 2023). "For example, (TRAV1-2+CD8+) MAIT cells, (NCAM1hiCD160+) NK cells, (CD4loCSF1R−CD33−CD14+) classical monocytes, and (CD33− HLA-DMA-CD14+) classical monocytes were associated with asymptomatic infection." (PMID 37795240, 2023). "Specifically, we determined the distribution of lymphocytes (CD3), NK cells (CD56), monocytic phagocytes (CD68), and myeloid-derived suppressor cells (MDSC; CD11B and CD33) in the lungs at 2 and 4 weeks post infection." (PMID 38338937, 2024). "The frequency of the CD33 rs3865444 CC allele increases in patients with AD, which subsequently upregulates microglial CD33 expression, hence increasing the immunosuppressive CD33 MDSC population, leading to enhanced susceptibility and more severe infection." (PMID 37962454, 2024). "The significance of this finding needs further elucidation given that CD33 represents a lineage marker associated with phagocytotic inhibition and CD64 is an early onset marker of clinical infection." (PMID 34576145, 2021). "There were several genes whose levels of mRNA expression were significantly (adjusted P< 0.05) different post-infection, including Fcgr1 and Cd36 which were up-regulated and Cd33 which was down-regulated." (PMID 31738750, 2019). "The authors found an induction of CD33+ cells in the peripheral blood during infection and increased human immune cell infiltration in the peritoneal cavity over time (days 1, 3, and 7 post-infection)." (PMID 39061322, 2024). "Targeting myeloid-lineage antigens, such as CD33 or CD123, is likely to be more problematic due to the risk of marrow suppression or aplasia placing patients at risk for severe associated complications including infection." (PMID 32582592, 2020). "In order to further improve this percentage and possibly augmenting CAR+ T-cell response to its specific target, we might concentrate anti-CD33.CAR-specific retroviral supernatant administration by increasing the Multiplicity of Infection (MOI)/cells ratio." (PMID 22272203, 2012). "Together, these data suggest that targeting CD33 can reduce HIV-1 replication and/or infection, indicating that CD33 at some point of the HIV-1 viral life cycle is required for effective viral propagation." (PMID 37506557, 2023). "First, CD33+ MDSCs were purified using FACsort from donor PBMCs and treated with mab-B2 and LILRB3-specific mab-B3, followed 1 day later by infection with Mtb and growth assay over 7 days." (PMID 35757769, 2022). "An older cohort study of 29 children with r/r CD33+ AML under GO reported severe leukopenia in 48%, severe infection with sepsis in 24% and severe pneumonia in 17% of patients, while one child died of fungal sepsis." (PMID 33807678, 2021). "Another pilot study of 12 children with r/r CD33+ AML, who received GO combined with busulfan and cyclophosphamide prior to AHSCT, reported severe infections in half of the patients, while one boy developed an IFD despite prophylaxis." (PMID 33807678, 2021). "We isolated splenocytes from two NRG-HIS mice and two NFA2-HIS/Flt3LG mice at 6-weeks post YFV-17D infection and sorted these cells by human CD45 (hCD45) or human CD33 (hCD33) expression." (PMID 30487575, 2018).
hematological malignancies (23 papers, 2017 to 2025). "For hematologic malignancies, such as ADCs targeting CD33, high antigen expression in both leukemic and normal hematopoietic progenitor cells likely explains the trend toward increased grade ≥3 AEs observed with DNA-damaging payloads." (PMID 40006625, 2025). "An anti-CD33 trispecific killer engager containing an IL-15 moiety has entered clinical testing against hematological malignancies (NCT03214666)." (PMID 36765035, 2023). "The combination of NK-mediated ADCC and cytokine signaling using TriKEs is a promising approach to clinical NK cell therapies, leading to a first-generation TriKE, GTB-3550 (CD16/IL-15/CD33) being investigated against CD33+ hematological malignancies (NCT03214666)." (PMID 37514187, 2023). "Alternative CAR targets were explored in the treatment of hematological malignancies such as CD3, CD5, CD7, CD33, CD138, SLAMF7 and NKG2D ligands in pursuit of for more effective strategies." (PMID 39633491, 2024). "The basic research and clinical experimental research of CAR-NK cells in hematological malignancies involve targets including CD19 and CD33." (PMID 36032149, 2022). "To extend the Malibu-Glo assay to other antigens for treatment of hematologic malignancies and solid tumors, we generated Malibu-Glo reagents based on scFvs targeting CD20, CD30, CD33, BCMA, CD138 and CS1." (PMID 32047180, 2020). "CAR-NK cells targeting several different antigens, including CD138, SLAMF7, CD19, CD20, CD33 and CD123, using both primary NK cells and NK cell lines, are currently being investigated in pre-clinical studies of both solid and hematological malignancies." (PMID 33304346, 2020). "Several ADCs have been designed and used for clinical use in hematologic malignancies and their targets include CD22,187–193 CD30,181,194–197 CD33,198–202 CD19,203–208 CD79,191,209,210 BCMA,211,212 CD37,213–215 CD138,216 CD56,217 CD74,218 GPRC5D,219 CD123,220 and CD25,221." (PMID 37591844, 2023). "We also discuss the basic research and ongoing clinical trials on emerging immune checkpoints (Galectin-9/Tim-3, CD70/CD27, LAG-3, and LILRBs) and on new targets for CAR-T cell therapy (CD22, CD33, CD123, BCMA, CD38, and CD138) for the treatment of hematologic malignancies." (PMID 31186046, 2019). "In fact, CD33 is not relevant only for hematologic malignancies." (PMID 40843358, 2025). "Other studies have further demonstrated that it improves CAR-T cell therapy safety through the use of iCasp9 in CD33-CAR-T cell against AML, interleukin-1 receptor accessory protein (IL-1RAP)-CAR-T cell against chronic myeloid leukemia and CD19-CAR-T cell against various hematological malignancies." (PMID 36248810, 2022). "Gemtuzumab ozogamicin, an anti-CD33 ADC, was once used in AML patients with their first relapse and no history of an antecedent hematologic disorder and a median age of 61 years." (PMID 37591844, 2023).
neurodegenerative disease (14 papers, 2017 to 2025). A disorder of the central nervous system characterized by gradual and progressive loss of neural tissue and neurologic function. "The strong genetic link between variants of CD33 and AD susceptibility suggests that targeting the common risk allele of CD33, which preferentially encodes the longer isoform (hCD33M) containing its glycan-binding domain, could be a treatment strategy in neurodegenerative disease." (PMID 31815204, 2019). "Genes linked to neurodegenerative diseases, such as GPNMB, GBA, CD33, and TREM2, were downregulated in ALI‐CO‐iMG 60d compared with 60d iMG." (PMID 41221983, 2025). "It contributes to understanding the cognitive profiles influenced by CD33 SNPs and posits CD33’s potential contribution to neurodegenerative disease progression, potentially intensified by HBV/HCV-induced inflammation." (PMID 40637125, 2025). "Regarding the MR findings of CD33 (SIGLEC‐3) in AD and SIGLEC‐9 in ALS, we note that several members of the SIGLEC protein family have been implicated for roles in neurodegenerative diseases, especially due to neuroinflammatory properties." (PMID 36504281, 2023). "Mutations in various phagocytosis genes (TREM2, complement receptor 1, CD33, APOE, etc.)were also implicated as risk factors for neurodegenerative diseases." (PMID 28340576, 2017). "Twenty-seven of these associations are known disease loci reported in GWAS, including APOE, MME, CD2AP, CD33 and IL34 for AD, and CD40, CD58, EVI5, IL7R and STAT3 for MS, and 23 associations represent previously unreported genetic associations with neurodegenerative diseases." (PMID 40037332, 2025). "In particular, mounting evidence from AD patients and experimental models indicates pivotal roles for TREM2, CD33, and CD22 in neurodegenerative disease progression." (PMID 37276426, 2023). "While increasing evidence indicates that ITAM/ITIM-containing immune receptors (i.e., TREM2, CD33, and CD22) are critically involved in AD progression, we still lack in-depth knowledge of the intracellular signaling molecules employed by these immune receptors to influence neurodegenerative disease." (PMID 37276426, 2023).
hematological cancers (7 papers, 2015 to 2025). "Globally, the R&D pipeline of CAR-T cells has expanded rapidly, including the exploration of new targets, such as BCMA, CD123, and CD33, as well as the expansion to new indications, such as the progression of hematological tumors to solid tumors." (PMID 31681259, 2019). "Hematological cancer targets for approved ADCs include CD33, CD30, CD22, and CD79b." (PMID 32111076, 2020). "Here we studied IGK expression in sorted CD33+CD19−CD138− myeloblasts from 18 AML patients, and monocytes and neutrophils from 12 patients with non-hematopoietic neoplasms and 8 healthy individuals." (PMID 26429876, 2015). "To date, only isolated singleton individuals with very low or absent CD33 expression and hematological cancer have been reported but the small number of cases precludes any generalization of potential biology." (PMID 40043053, 2025). "The examples of CD33 and CD30 suggest that the lineage-specific expression profile and the efficient internalization are two of the key factors determining the successful ADC targets for hematological cancers." (PMID 32111076, 2020).
blood cancers (5 papers, 2019 to 2025). "To incorporate these ideas and findings in the context of AML and other blood cancers, we tested a variety of bispecific constructs targeting CD33, CD16b and other blood-related antigens." (PMID 40191207, 2025). "Gemtuzumab ozogamicin (Mylotarg®) against CD33, approved for blood cancer in 2000 and 2017, was endocytosed through the endosome/lysosome pathway in CD33-expressing HL-60 cells." (PMID 36546903, 2022).
neurological disease (4 papers, 2021 to 2025). "As one of these DMPs mapped to a Single Nucleotide Polymorphism (SNP) associated with AD risk, it will be interesting to assess to what degree CD33 influences neurological disease progression in HIV-1+ individuals suffering from HAND." (PMID 37506557, 2023). "Seven of these proteins have cis-acting pQTLs that colocalise with or are causal for neurological diseases: DDR1, IL12, NEP, CD33, DPEP1, GPNMB, and LEPR." (PMID 34857772, 2021). "Ten proteins showed co-localization with a neurological disease using both plasma protein abundance and plasma mRNA abundance (SIRPA, CTSH and CD33 with AD; and ASF1A, FCRL3, VEGFB, TYMP, PVALB, LMAN2 and CD5 with MS)." (PMID 40037332, 2025).
psychiatric diseases (4 papers, 2019 to 2025). "The expression amounts of CD33 in the monocytes are associated with monocyte function and amyloid biology in patients with Alzheimer’s disease, suggesting an important role for myeloid lineage cells in the development of neurological and psychiatric diseases." (PMID 31767892, 2019).
immune dysfunction (2 papers, 2016 to 2025). "This could result in an ascertainment bias that would underpower the ability to detect a pathophysiological role of CD33 on the background pre-existing immune dysfunction." (PMID 40043053, 2025).
infectious disease (1 paper, 2016). A disorder directly resulting from the presence and activity of a microbial, viral, or parasitic agent in humans. "In studies in infectious diseases (HIV, HCV), gMDSC were defined to lack the expression of CD14 but to express CD15/CD33/CD11b whereas mMDSC were characterized as CD14+/CD11b+/HLA-DR−/low cells or additionally CD33+ cells." (PMID 26733325, 2016).
CD33 also shares sentences with these, for which no sentence is quoted: colorectal cancer (8 papers); systemic mastocytosis (5); Thrombocytopenia (5); chronic lymphocytic leukemia (4); multiple sclerosis (4); amyotrophic lateral sclerosis (3); frontotemporal dementia (3); asthma (2); bone marrow fibrosis (2); erythroleukemia (2); head and neck squamous cell carcinoma (2); ischemia (2); pancreatic adenocarcinoma (2); renal carcinoma (2); acute GVHD (1); adenocarcinoma (1); anaplastic large cell lymphoma (1); autism spectrum disorder (1); autoimmune disease (1); autoimmune hepatitis (1); benign prostatic hyperplasia (1); bladder tumors (1); brain tumor (1); Burkitt lymphoma (1); carcinoma in situ (1); Cerebellar atrophy (1); cholangiocarcinoma (1); chronic pancreatitis (1); Cirrhosis (1); coagulopathies (1).
A further 45 diseases each share a sentence with CD33 in 1 paper.